TNF (tumor necrosis factor)
Diseases named in the same sentence as TNF in open-access papers (continued):
Sharing a sentence is not in itself a finding about the gene and the disease.
viral infection (continued). "NF-B pathway is activated by a variety of extracellular factors such as tumor necrosis factor alpha (TNF), interleukin 1 (IL1), growth factors, bacterial or viral infections or oxidative stress." (PMID 34026749, 2021). "On the other hand, LGALS3BP expression was found to be induced by viral infection and in response to a variety of cytokines unleashed by inflammatory processes, including IFN-α (Interferon), IFN-β, IFN-γ, TNF-α (Tumor Necrosis Factor)." (PMID 34565385, 2021). "This process controls cytokines production when stimulated by different factors, such as bacterial or viral infections, and is dependent of several factors, such as IL-1 β, TLR activation by LPS and TNF-α." (PMID 34204279, 2021). "TLR3 recognizes dead virus-infected cells and generates IFN-1 as well as the proinflammatory cytokines TNF, IL1, and IL6, allowing the host to develop a defense against viral infections." (PMID 34659656, 2021). "To measure the speed of cell decision, we treated fibroblasts with dose titrations of TNF, infected them with MOI 10 of HSV-1, and imaged viral infection and cell death for 48 h." (PMID 34016976, 2021). "Th1 cells, which produce cytokines such as IFN-γ, tumor necrosis factor alpha (TNF-α), and interleukin (IL)-2, play an important role in protection against viral infection." (PMID 33688034, 2021). "Recently, it has been demonstrated that when GSDME is stimulated by chemotherapeutic agents, tumor necrosis factor (TNF) and viral infection, it is activated by caspase-3 which is involved in apoptotic signaling." (PMID 35118075, 2021). "Various extracellular stimuli can activate necroptosis, including TNF, interferon, and Toll-like receptor (TLR) signaling as well as viral infection." (PMID 34646380, 2021). "In a nutshell, our findings showed that TNF-α enhanced viral entry of SARS-CoV-2, which in turn upregulated TNF- α, leading to a vicious circle of viral infection and the accumulation of the cytokines." (PMID 34576032, 2021). "All these virus infection induced gene transcriptions of IFNβ, ISG56, TNFα, IL1β and IL8 were reduced in in LGP2-/-, RIG-/- and MDA5-/- PAMs compared with control PAMs." (PMID 34093517, 2021). "Virus infection induced a robust increase of IL-6, CXCL8, TNF-α, CXCL10, COX-2, and RANTES in mRNA level with a dose-dependent manner." (PMID 34552653, 2021). "Consistently, it was reported that not only interferon treatment or viral infection increased ACE2 levels, several inflammatory cytokines stimulation, such as TNFα, IL6 and IL1β, also increased the level of ACE2." (PMID 34867400, 2021). "Anti-TNF therapy does reduce CD8+ T cell proliferation, which can result in viral infection or reactivation." (PMID 34561436, 2021). "By inhibiting replication of the virus, elderberries significantly increase the production of pro-inflammatory cytokines (IL-1β, TNF-α, IL-6, and IL-8), especially TNF-α, which enhances the response of macrophages to a viral infection." (PMID 34578858, 2021). "NK cells are cytotoxic lymphocytes that belong to the innate lymphoid cell (ILC) family and are known to defend against tumors and viral infections mainly through the production of interferon (IFN)-γ and tumor necrosis factor (TNF)." (PMID 34576042, 2021). "During the early stage of viral infection, cytokines (IL-1, IL-2, IL-8, IL-10, CCL2, CCL7, IFN-α, IFN-β, and TNF-α) have essential functions in the recruitment of immune cells, defense against the infection, and promotion of inflammation." (PMID 34603560, 2021). "Compound 4a antagonist binds to TLR3/dsRNA to suppress TLR3 activity in gastrointestinal viral infections as well as the expression of downstream TLR3/dsRNA signaling pathways, including TNF-α and IL-1β." (PMID 34659656, 2021). "TNF-α is a key factor for viral crossing of the BBB, and IL-10 was also proved to facilitate viral infection." (PMID 33597934, 2020).
viral infection (continued). "An essential function of NK cells, especially in viral infections, is to release cytokines, such as IFN-γ and tumor necrosis factor-α (TNF-α) as immune-defensive agents." (PMID 32161581, 2020). "The study also revealed the multifunctional synergetic mechanisms of SM, including certain virus infection and cancer, and PI3K-Akt, TNF, and IL-17 signaling pathway." (PMID 33204288, 2020). "Further, in many viral infections, TNF-α and IFN-I are the essential effector molecules that drive the innate immune response where TNF-α works in synergy with IFN-I." (PMID 32575459, 2020). "It has been found that most of the stimuli that activate NF-κB in the immune system, such as tumor necrosis factor-α (TNF-α) or interleukin 1 (IL-1), viral infections, and oxidative stress, exert the same effect in the CNS." (PMID 32265684, 2020). "To date, CD4+ and CD8+ T cells capable of co-producing IFN-γ, TNF-α and IL-2 (namely multifunctional CD4+ and CD8+ T cells) have been considered to be important for controlling various viral infections." (PMID 33142799, 2020). "In general, CD8+ T cells can eliminate viral infection by generating effector cells, induce cytotoxicity, IFN-γ, and TNFα." (PMID 33072068, 2020). "The initial primary defense response of animals to viral infection is the production of Interferon-alpha (IFN-α) (a type 1 interferon), often followed by inflammatory cytokines such as tumor necrosis factor (TNF) and interleukin-1 (IL-1)." (PMID 32849384, 2020). "IRF1 expression in cells can be induced by virus infection and various cytokines as well as other stimuli, such as dsRNA, IFN-α/β, TNF, and IL-1, in different cell types." (PMID 32983049, 2020). "In response to viral infection, CD226 KO mice showed delayed lymphocytic choriomeningitis virus (LCMV) clearance, with reduced IFNγ and TNFα production by virus-specific CD8+ T cells." (PMID 33013915, 2020). "We detected TNF-α and IFN-γ production in microglial cells, which probably occurred in response to the viral infection in the brain." (PMID 32486462, 2020). "NK cells suppress viral infections by multiple ways including cytolysis of infected cells and secretion of a variety of cytokines including IFN-γ, TNF-α, GM-CSF and MIP-1α/β." (PMID 32320436, 2020). "Other pathways, such as Janus Kinase (JAK)-STAT signaling pathway, Tumor Necrosis Factor (TNF) signaling pathway and cytokine-cytokine receptor interactions were exclusively up-regulated pathways in virus infection." (PMID 32075271, 2020). "ISG15 expression is normally induced in host cells by a variety of factors, including viral infection, TLR ligands such as lipopolysaccharide and poly IC, tumor necrosis factor-α, or type I, II, and III IFNs." (PMID 33024031, 2020). "The maturation of DCs, stimulated by inflammatory cytokines like tumor necrosis factor alpha (TNF-α) and IL-1, is very important event in the immune response of a host during a viral infection." (PMID 33262955, 2020). "This is based on the fact that, in the presence of an exacerbated inflammatory response to viral infection, pro-inflammatory cytokines, such as interleukin-6 (IL6) and tumor necrosis factor alpha (TNF-α), are released at high levels." (PMID 33233769, 2020). "Specifically, NK cells are cytotoxic and defend against tumors and viral infections, mainly through production of cytotoxic granules, interferon (IFN)-γ, and tumor necrosis factor (TNF)." (PMID 32983138, 2020). "Conversely, previous studies on viral infections in swine have shown that the CD4+ Tcm subset was capable of IFN-γ, TNF-α and/or IL-2 production." (PMID 33584671, 2020). "As in regular viral infection, BTV12 activated monocytes normally and strongly, indicated by the TNF-α and IL-1β expressions, but activated the Th2 pathway poorly, indicated by the IL-4." (PMID 33375108, 2020). "When expressed independently of virus infection, vICA binds to the pro-domain of CASP8 and prevents TNF-, Fas-, or RIPK3 inhibitor-dependent apoptosis in fibroblasts." (PMID 33126536, 2020).
viral infection (continued). "In a previous study on the role of CARD9 in proinflammatory cytokine production during viral infections, in vitro stimulation of CARD9−/− DCs with influenza A virus (IAV) also showed an impaired IL-6 and TNF-α production." (PMID 30917612, 2019). "At early viral infection, NK cells can direct eliminated infected cells through cytolytic activity and cytokine secretion, such as IFN-γ and tumor necrosis factor alpha (TNF-α)." (PMID 32038620, 2019). "After virus infection, the levels of IFN-β, TNF-α and IL-6 were markedly increased compared with the control uninfected group (P < 0.01 or P < 0.05)." (PMID 31551774, 2019). "Generally, CD8 T cells can control viral infection through several mechanisms, including direct cytotoxicity, and production of pro-inflammatory cytokines such as IFN-γ and TNF-α." (PMID 31552052, 2019). "Both IFN- and TNF- belong to type I interferon (IFN), which contribute to the innate immunity against viral infection." (PMID 30911327, 2019). "The mRNA expression levels of IL-1β, IL-6, IL-8, IFNs, TNF-α, Mx, and OASL were significantly upregulated during the viral infection." (PMID 31288442, 2019). "Cytokines including GM-CSF, IL-2, IL-1β, TNF-α, IFN-γ, and IL-10 are key molecules that regulate innate and adaptive immune responses to viral infection." (PMID 31412594, 2019). "Mice infected with a mixture of rgH5N1 virus and F.G.B displayed lower levels of inflammatory cytokines (IL-6, TNF-α) in lung and in BALF compared to virus infection of the control mice." (PMID 30200514, 2018). "TNF is reported to negatively regulate the expansion of effector CD4+ and CD8+ T cells during viral infection through apoptosis, thus subsequently limiting the T cell memory compartment." (PMID 30314507, 2018). "Because virus infection can lead to the production of the pro-inflammatory cytokines IFN-γ, TNF-α, IL-1ß, and IL-6, which contribute to inflammation, the expressions of these cytokines were measured." (PMID 28417913, 2017). "Many different bacterial and viral infections ultimately induce PGE2 via the activation of various toll-like receptors (TLRs) and TNF-α." (PMID 28445497, 2017). "IL-10 down-regulates the immune response after virus infection by inhibiting IFN-γ production, antigen presentation, and macrophage production of IL-1, IL-6, and TNF-α." (PMID 28086978, 2017). "NK cells with phenotype marker CD3-CD16 + CD56+ are the type of cytotoxic lymphocytes critical to the innate immune system and secrete TNF-α and IFN-γ to control viral infection." (PMID 28174597, 2017). "The levels of either gene expression or cytokine proteins (IL-1α, TNFα, IL-6, CXCL10, CCL5, CCL2, CCL3, CCL4, and CCL5) in RSV-infected PMФ are comparable to the H5N3 virus infection." (PMID 28558796, 2017). "Considering that interferon expression is mainly IRF3/IRF7-mediated while expression of TNFα and CXCL8 is mainly NFκB-mediated, it appears that azithromycin predominantly affects IRF signalling pathways after viral infection." (PMID 27350308, 2016). "Thus, anti-TNFα therapies could be utilized to treat certain viral infections." (PMID 27351838, 2016). "In terms of viral infections, hepatitis B (HBV) and hepatitis C (HCV) are the best studied in patients on TNFα inhibitors." (PMID 27818806, 2016). "It would be of interest to inhibit TNFα, or potentially TNFR2, in SVCV-infected carps for the treatment of this viral disease that produces abundant losses in aquaculture worldwide." (PMID 27351838, 2016). "We next measured levels of immunomodulatory mediators in lung homogenates and report that viral infection in fibrotic lungs (Bleo+MHV-68) led to a significant increase in lung levels of CCL2, IL-1β, TNFα and IL-10 above the levels detected for Bleo lungs." (PMID 26138704, 2015). "Here, to gain a better understanding of how virus infection and mAb treatment affected host immune response, we analyzed the levels of IFN-γ and TNF-α in the lung." (PMID 25888728, 2015).
viral infection (continued). "The activation of PRRs induces the expression of cytokines and antiviral proteins, including IL-1β, IL-2, TNF-α, MX, and OAS, which alert the immune system to viral infection." (PMID 26005441, 2015). "Additionally, NK cells can inhibit the spread of viral infections via their cytolytic action against infected cells and the production of proinflammatory cytokines and immune modulators such as interferon gamma (IFNγ) and the tumor necrosis factor alpha (TNFα)." (PMID 26296209, 2015). "Exogenous G6PD or IDH1 expression inhibited the expression of HSCARG, resulting in increased expression of TNF-α and MX1 and reduced viral gene expression upon virus infection." (PMID 26694452, 2015). "These experiments place pathologic complement activation downstream of viral infection, MAVS signaling, and TNF-α signaling and indicate that it contributes to the sepsis-like syndrome." (PMID 24743949, 2014). "M1 macrophages can produce pro-inflammatory cytokines/mediators such as IL-1β, IL-6, tumor necrosis factor (TNF)-α, CC-chemokine ligand 2 (CCL2), ROS, and NO, and play a central role in host defense against bacterial and viral infections." (PMID 25429645, 2014). "Several pro-inflammatory cytokines (e.g. IL-1, IL-6, TNF-α, and IFN-β, etc) are induced by oxidant stress, cytokines, and virus infection, which play a role in host cell damage, chronic inflammation, and other immunoresponses." (PMID 25548009, 2014). "The production of specific cytokines such as the tumor necrosis factor (TNF)-α, interleukin (IL)-1, IL-6 and IL-10, and chemokine IL-8, are induced by viral infection, as demonstrated by an analysis of the sera of pandemic influenza-infected patients." (PMID 25254368, 2014). "It has been shown for virus infections, including HIV and SIV, that infection of cells, particularly macrophages, leads to the induction of innate immune responses, type I IFN and TNFα." (PMID 23988154, 2013). "A curious observation was the inverse correlation of the expression levels of the transcripts of IL-6, TNF-α, CXCL9, CCL2 and CCL3 and the virus infection dose." (PMID 24086645, 2013). "The significance of the induction of TNF-α and IL-6 expression following the TLR7/8-mediated response to ssRNA virus infection is not fully known." (PMID 24191131, 2013). "Firstly, It has been suggested that IL-17A induces TNF-α and IL-6 expression; therefore, we measured the TNF-α and IL-6 protein levels on the day 7, 60 and 90 post viral infection in the blood." (PMID 23977238, 2013). "Here we show that secretion of WNT2B and WNT9B and stabilization of β-catenin (CTNNB1) upon virus infection negatively regulate expression of representative inducible genes IFNB1, IFIT1 and TNF in a CTNNB1-dependent effector mechanism." (PMID 23785285, 2013). "As expected, TNF-α, previously shown to inhibit apoE in macrophages, led to a similarly reduced production as did IFN-α, a cytokine normally induced by viral infection." (PMID 24244577, 2013). "Many factors, such as UV radiation, cytokines (e.g., IL-1β, TNF-α, IFN-γ, and IL-15), viral infections (hepatitis B or C, HIV infection) can induce expression of Fas in epidermis." (PMID 22778762, 2012). "At this time after virus infection, VEGF mRNA levels were >50-fold greater than levels found in mock-infected monolayers (p = <0.04), but TNF-α mRNA levels were only ∼3-fold greater." (PMID 22570607, 2012). "This is in contrast with the significantly higher TNF-alpha mRNA levels in MM after HPAIV H5N1 virus infection compared to seasonal H3N2 and pH1N1 virus infection observed in our and previous studies." (PMID 21731493, 2011). "Our results indicated that the release of CCL2 and IL-10 from DCs was positively related to viral infection while the production of IFN-α and TNF-α was negatively related to viral replication." (PMID 21269456, 2011).
viral infection (continued). "Indeed, TNFα can have a direct effect on viral tropism by altering the expression of the cell surface receptors used by viruses; and depletion of this cytokine using TNFα blockers might facilitate the development or reactivation of the viral infection." (PMID 22206025, 2011). "To confirm that loss of MAVS is responsible for increased cytokine production induced by γHV68, we “reconstituted” MAVS expression by lentivirus in Mavs−/− MEFs, and examined gene expression of cytokines (such as TNFα and CCL5) in response to viral infection." (PMID 22110409, 2011). "TNFα response occurs concomitant with type I IFN responses and is one of the first responses to viral infection of macrophages." (PMID 20019816, 2009). "The activation of mononuclear system cells occurs due to a hypersecretion of proinflammatory cytokines (IFNγ, TNFα, IL6, IL10, M-CSF), as a consequence of a triggering agent, which is often a viral infection." (PMID 18834507, 2008). "By extrapolation of the results obtained with clone SLY-10, MCP-1 is likely to be triggered by levels of antigen characteristic of in vivo viral infection settings since its position within the functional hierarchy was similar to that of IFN-γ and TNF-α." (PMID 17393387, 2007). "The activation of this factor during early stages of viral infection leads to the expression of several immune response genes; such as pro-inflammatory cytokines (IFN-β, TNF-α, IL-6, IL-8), chemokines (RANTES) and adhesion molecules (ICAM-1, VCAM-1)." (PMID 17971236, 2007). "Physiological stimuli for the synthesis of TNFα are IL-1, bacterial endotoxins, TNF, platelet derived growth factor (PDGF), and Oncostatin M. In fibroblasts the synthesis of TNFα is stimulated by IFNβ, TNFα, PDGF, and viral infections." (PMID 17034639, 2006). "TNFα levels rise and fall in the plasma during AHI coincident with viral load, and TNFα has been shown to inhibit GC formation in other bacterial and viral infections." (PMID 39932316, 2025). "After virus infection, Piezo1 channel activation was downregulated by GsMTx4 treatment, leading to reduced PAD4 expression, ROS production and NET formation in neutrophils, and TNFα and NOS2 expression was decreased in macrophages from the BALF and lung." (PMID 39890818, 2025). "In our study, the transcription levels of TNF-α, IL-18, IFN-α, and IFN-λ3 were reduced in the early stage of virus infection (within 6 dpi), the transcription levels increased gradually but were maintained at a level equivalent to that of the control group from dpi 12 onward." (PMID 41293456, 2025). "In particular, T helper 1 (Th1) lymphocytes are known to play a fundamental role in the immune response against viral infections through the release of key cytokines such as IFN-γ, interleukin (IL)-2, and tumor necrosis factor (TNF)-α, also known as Th1 cytokines." (PMID 41246331, 2025). "KEGG analysis identified significant involvement of PT DEGs in pathways related to cytokine signaling, cell adhesion molecules, tumor necrosis factor (TNF) signaling, PI3K–AKT signaling, thyroid hormone synthesis, bacterial infections, and certain viral infections." (PMID 39987090, 2025). "Additionally, CCL5, which is primarily expressed by T-cells and monocytes, is known to be induced by TNF-α and IFN-γ during pathogen infections, particularly viral infections." (PMID 39844283, 2025). "Among immune effectors, CD8 cytotoxic T lymphocytes (CTLs) play a crucial role in controlling viral infections by eliminating infected cells and orchestrating antiviral responses through the secretion of cytokines such as interferon-γ (IFN-γ) and tumor necrosis factor-α (TNF-α)." (PMID 40665369, 2025). "During the viral infection course, increased synthesis of proinflammatory markers such as C-reactive protein (CRP), tumor necrosis factor-alpha (TNF-α), ferritin and interleukins increase consumption of albumin and muscle protein, which is the main cause of susceptibility to malnutrition." (PMID 40429378, 2025).